STAT5B (signal transducer and activator of transcription 5B)
Diseases named in the same sentence as STAT5B in open-access papers (continued):
Sharing a sentence is not in itself a finding about the gene and the disease.
acute myeloid leukemia (9 papers, 2008 to 2025). Acute myeloid leukemia (AML) is a group of neoplasms arising from precursor cells committed to the myeloid cell-line differentiation. "Four of the seven dysregulated TFs, Atf1, Fos, Rxra and Stat5b, have been previously associated with acute myeloid leukemia, and ninety-six genes that were differentially expressed in APL were identified as targets of these TFs." (PMID 18291030, 2008). "Similarly, mutations in STAT5B have been implicated in various hematological malignancies, including acute myeloid leukemia (AML) and chronic lymphocytic leukemia (CLL)." (PMID 39979591, 2025). "For instance, in ~30% of acute myeloid leukemia (AML) cases, STAT5B is activated by mutated FLT3 (Fms-Like Tyrosine Kinase 3)." (PMID 31717342, 2019). "Signal transducers and activators of transcription 5A and 5B (STAT5A and STAT5B) are crucial downstream effectors of tyrosine kinase oncogenes (TKO) such as BCR-ABL in chronic myeloid leukemia (CML) and FLT3-ITD in acute myeloid leukemia (AML)." (PMID 31861239, 2019). "Finally, the inclusion of STAT1, STAT5B, and STAT3 is of relevance given the cross talk between retinoid receptors and this group of transcription factors in acute myeloid leukemias." (PMID 25888236, 2015).
eczema (9 papers, 2012 to 2025). "Conversely, STAT5B deficiency impairs regulatory T-cell function, facilitating multi-organ autoimmune manifestations such as eczema, juvenile idiopathic arthritis, and immune thrombocytopenia." (PMID 40831950, 2025). "Regarding the STAT5b deficiency, besides short stature due to growth hormone (GH) insensitivity, the clinical features included eczema, chronic diarrhea, lymphoid interstitial pneumonia, cytopenias, and increased susceptibility to infections." (PMID 33330291, 2020). "Altogether, we demonstrate that specific heterozygous STAT5B germline mutations exert dominant-negative effects resulting in STAT5B deficiency clinically characterized by significant postnatal growth impairment, mild GH insensitivity, eczema, and elevated IgE." (PMID 29844444, 2018). "In conclusion, we report the first germline dominant-negative STAT5B mutations observed in patients who demonstrated milder but significant postnatal growth impairment, mild GH insensitivity, eczema, and elevated IgE." (PMID 29844444, 2018). "Altogether, the clinical manifestations (i.e. growth impairment, elevated IgE, eczema) suggest variability in penetrance of the mutant genotypes and are consistent with the milder phenotype of AD STAT5B loss-of-function mutations." (PMID 29844444, 2018). "Most subjects with STAT5b deficiency show severe eczema, and autoimmune disease (juvenile idiopathic arthritis, autoimmune thyroiditis, idiopathic thrombocytic purpura) which are thought to be associated with Treg dysfunction." (PMID 22912632, 2012). "Mild eczema was reported for the majority of carriers of dominant-negative STAT5B mutations." (PMID 29844444, 2018). "Future screenings of GHIS patients will validate whether the additional features of eczema and elevated IgE may be indications of potential inactivating AD STAT5B mutations." (PMID 29844444, 2018). "Recently, dominant negative heterozygous STAT5B mutations were detected in three families with GH insensitivity and immune dysregulation, where the affected individuals presented eczema and high IgE levels, without infections." (PMID 33330291, 2020). "Here we report dominant-negative, inactivating STAT5B germline mutations in patients with growth failure, eczema, and elevated IgE but without severe immune and pulmonary problems." (PMID 29844444, 2018).
glioblastoma (9 papers, 2014 to 2024). The most malignant astrocytic tumor (WHO grade IV). "A reduced activity of the hypoxia/HIF-1α/STAT5b signaling pathway is associated with epileptogenicity in glioblastomas." (PMID 30621209, 2019). "STAT5b was identified as the predominant isoform in glioblastoma, particularly in EGFRvIII expressing cells associated with tumor aggressiveness and increased cell invasion." (PMID 27029073, 2016). "STAT5b phosphorylation at Y699 was associated with poor outcome in glioblastoma and interacted with EGFRvIII in the nucleus of glioma cells, and this complex has been found to associate with promoter sequences and regulate gene expression." (PMID 27029073, 2016). "Finally, our correlation analyses identified STAT5B as a druggable target whose expression was associated with therapy resistance, yet with rather low expression dynamics across the glioblastoma cell line panel." (PMID 36906590, 2023). "Interestingly, STAT5b protein expression associated with glioblastoma patient survival in our population of patients." (PMID 30621209, 2019). "In fact, STAT5B can be activated by SFKs and mediate survival signalling in glioblastoma cells through direct activation of the BCL2L1 promoter." (PMID 33478100, 2021). "Interest in STAT5 signaling in glioblastoma is growing, as multiple studies have shown that STAT5b drives proliferation and invasion in glioma." (PMID 30621209, 2019). "Accordingly, the knockdown of STAT5b suppressed transformation by EGFRvIII and sensitized glioblastoma cells to cisplatin-induced apoptotic death." (PMID 27029073, 2016). "Epileptogenic GBMs correlate with decreased hypoxia/ HIF-1α/STAT5b signaling compared to glioblastomas that do not present with epilepsy." (PMID 30621209, 2019).
glioma (9 papers, 2016 to 2024). A benign or malignant brain and spinal cord tumor that arises from glial cells (astrocytes, oligodendrocytes, ependymal cells). "Survival analysis indicated that the upregulation of STAT1/2/3/5A/6 and downregulation of STAT5B expression was associated with poorer overall survival in glioma." (PMID 34276757, 2021). "A previous report in established glioma cell lines shows that EGFRvIII-induced activation of STAT5B through Src family kinase Fyn induces expression of BCL-XL and contributes to resistance to cisplatin." (PMID 38892466, 2024). "The expression of STAT1/2/3/5A/6 members were significantly higher and positively correlated with IDH mutations, while the expression of STAT5B was lower and negatively correlated with IDH mutations in glioma." (PMID 34276757, 2021). "The expression of signal transducer and activator of transcription 5B (STAT5b), a transcription factor that promotes the malignant progression of gliomas 29, was abnormally upregulated in TMZ resistant cells." (PMID 32194873, 2020). "In summary, ATRX was upregulated by DNA demethylation mediated by STAT5b/TET2 complex in TMZ resistant glioma cells." (PMID 32194873, 2020). "STAT3 effects in gliomas have been suggested to depend on STAT5b activity possibly attributed to their close proximity in chromosome 17q." (PMID 31698775, 2019). "Moreover, STAT5B can drive tumour progression in a PDGFB-driven glioma model and this involves increased BCL2L1 expression." (PMID 33478100, 2021). "STAT5A and STAT5B are predominantly located in the cytoplasm of glioma cells." (PMID 34276757, 2021). "TET2, as an interaction partner of the transcription factor EBF1, regulates DNA methylation in gliomas 44, STAT5b also could recruit TET2 in specific site to promote DNA demethylation." (PMID 32194873, 2020). "Our results indicated that ATRX was upregulated via DNA demethylation mediated by STAT5b/TET2 complex in TMZ resistant glioma cells and that ATRX promoted PARP1 stabilization through down-regulating FADD by suppressing of H3K27me3 enrichment in FADD promoter region." (PMID 32194873, 2020). "STAT1, STAT3, STAT5A, STAT5B, and STAT6 mRNA expression levels were significantly upregulated in glioma (including GBM, astrocytoma, oligodendroglioma, and anaplastic astrocytoma), compared with normal brain tissues or neural stem cells." (PMID 34276757, 2021). "We found that the expression of STAT5b, a transcription factor that could be phosphorylated in EGF or HGF dependent manner and promoted the malignant progression of gliomas 29, 43, was abnormally upregulated in TMZ resistant cells." (PMID 32194873, 2020).
Obesity (9 papers, 2012 to 2024). Accumulation of substantial excess body fat. "Loss of GH-activated liver STAT5b activity leads to metabolic disturbances linked to obesity as well as fatty liver disease, the most common liver disease in humans." (PMID 26959237, 2016). "This is supported by original findings that STAT5b-deleted male mice become obese in later life and that STAT5b deletion in a mature human was associated with obesity." (PMID 23761784, 2013). "This role is supported by the original findings that STAT5b-deleted male mice become obese in later life and that STAT5b deletion in a mature human was associated with obesity." (PMID 24281711, 2012). "GHR-JAK2-STAT5 signaling deficiency has also been studied by the mutagenesis of GHR in mice, a model that causes severe obesity in mature mice in proportion to the loss of STAT5b activity." (PMID 24281711, 2012). "A mutation in the STAT5B gene in a mature human was also associated with striking obesity." (PMID 26959237, 2016). "Collectively, STAT5B-CA-mediated Treg cell overactivation redistributes the iron pool from liver and spleen to adipose tissues, which may contribute to the alleviation of metabolic stress associated with diet-induced obesity." (PMID 35874700, 2022). "Thus, the functional impairment of STAT5b could be a molecular initiating event that leads to several adverse outcomes, including obesity, fatty liver, and liver cancer." (PMID 26959237, 2016). "STAT5B, a promotor of adipogenesis, differentiated MIS-C patients with pre-existing obesity." (PMID 38632526, 2024).
T cell lymphoma (9 papers, 2013 to 2021). "Screening for known activating mutations in STAT3 or STAT5B identifies the presence of the STAT5BN642H driver mutation in feline enteropathy-associated T cell lymphoma in 7 out of 42 (16.67%) samples in total." (PMID 34680385, 2021). "To date, activating mutations of the JAK/STAT core cancer pathway and particularly the STAT5B oncoprotein have been identified in human enteropathy-associated T cell lymphoma." (PMID 34680385, 2021). "66.7% of cases had mutations in genes of the JAK-STAT signaling pathway which was known as a major oncogenic mechanism in T cell lymphomas, including STAT5B mutations (4/9), JAK3 mutations (3/9), and STAT5A mutations (2/9)." (PMID 34895266, 2021). "The activation of STAT3 and STAT5B in feline alimentary T cell lymphomas is comparable to the human disease, therefore, we continued to analyse the genomic status of the respective STAT genes." (PMID 34680385, 2021). "The entire STAT3 gene and the hotspot SH2-domain of STAT5B were screened by targeted amplicon sequencing in 63 patients with T-cell lymphoma." (PMID 32188095, 2020). "Furthermore, we have shown these cell lines to bear several characteristics which are typical for this type of T-cell lymphoma including the rearranged chromosome i(7q) and specific mutations in HIST1H3B, KDM7A, SETD2 and STAT5B." (PMID 31143370, 2019). "Indeed, NOD mice with the Stat5b transgene (NOD.Stat5bTg) developed high incidence of CD8+ T cell lymphoma with earlier age of onset." (PMID 23457589, 2013). "However, no studies focus on STAT5B mutation in systemic EBV + T-cell lymphoma of childhood and PTCL-NOS was published." (PMID 29615001, 2018). "However, low incidence of CD8+ T cell lymphoma was observed in B6 transgenic mice overexpressing a wild-type Stat5b (B6.Stat5bTg) despite of undetectable Stat5b phosphorylation and the rate of lymphomagenesis was markedly enhanced by immunization or the introduction of TCR transgenes." (PMID 23457589, 2013). "We next investigated why NOD.Stat5bTg mice developed T cell lymphoma in much higher incidence and at earlier ages compared to both B6 and NOD/B6 F1 mice even though the same Stat5b transgene is present in these three different transgenic strains." (PMID 23457589, 2013).
ovarian carcinoma (8 papers, 2010 to 2025). A malignant neoplasm originating from the surface ovarian epithelium. "While breast and ovarian cancers also demonstrated potential survival benefits associated with high STAT5B expression, these associations were less consistent across studies." (PMID 41301421, 2025). "Upon oncoproteomic analysis, STAT5B was overexpressed in ovarian cancer that recurred after chemotherapy." (PMID 36524006, 2022). "Our current results show that high mRNA expression of STAT5a and STAT5b related to an improved OS of ovarian cancer, which is consistent with only previous study to explore the impact of STAT5 on the prognosis of ovarian cancer patients." (PMID 28536310, 2017). "Inhibition of either expression or activity of RELA and STAT5B decreased Bcl-xL expression levels and increased carboplatin sensitivity in carboplatin-resistant ovarian cancer cells." (PMID 20585448, 2010). "Although our proteomics screening identified both STAT5A and STAT5B as upregulated proteins in recurrent ovarian cancer, we focused on studying STAT5B in our shRNA screens because it was also markedly upregulated in our chemoresistant cell lines." (PMID 20585448, 2010). "In this study, we used proteomic analysis and functional screening to identify RELA and STAT5B as the two major proteins involved in carboplatin resistance in ovarian cancer." (PMID 20585448, 2010). "Similarly, one of the major findings in our study was the upregulation of RELA and STAT5B in recurrent post-chemotherapy ovarian cancer cells." (PMID 20585448, 2010). "Further research confirmed that STAT5B and RELA (NF-kappaB p65) were responsible for carboplatin resistance in ovarian carcinoma." (PMID 36524006, 2022). "Differentially, in high-grade (G3, G4) ovarian cancer, STAT1, 2, 4, and 5A were highly expressed, while STAT3 and STAT5B were mostly lowly expressed." (PMID 36524006, 2022). "Our results show that high mRNA expression of STAT1, STAT4, STAT5a, STAT5b, and STAT6, are correlated to a better OS of ovarian cancer patients, especially the high level of STAT1 and STAT4 are significantly related to a favorable OS for serous ovarian cancer patients." (PMID 28536310, 2017). "With regard to clinical stages, while STAT5a, STAT5b, and STAT6 were related to a positive OS both in stages I/II and III/IV ovarian cancer patients, STAT1 and STAT4 were correlated to a favorable OS in stages III and IV ovarian cancer patients." (PMID 28536310, 2017). "We found that similar to dasatinib, STAT5B-specific shRNA synergized with BMS-345541 in conferring the best chemosensitization effect, again indicating that co-inhibition of STAT5 and NF-κB is a promising strategy for the treatment of carboplatin-resistant ovarian cancers." (PMID 20585448, 2010).
viral infection (8 papers, 2015 to 2025). "Lastly, we demonstrate that Olah, a gene known to drive life-threatening viral disease in humans, is regulated by STAT5B through a candidate four-partite super-enhancer." (PMID 40163145, 2025). "Our previous studies have demonstrated that RSV and RBSDV infection can activate the JAK-STAT pathway, promote the accumulation of LsSOCS5 regulated by the transcription factor STAT5B, and facilitate persistent viral infection in insect vectors." (PMID 40162791, 2025). "Next, after RSV crude extracts were injected into the hemolymph of nonviruliferous SBPHs, the protein levels of SOCS5 and phosphorylated STAT5B gradually increased during the course of viral infection." (PMID 36928081, 2023). "To determine the role of JAK-STAT pathway in viral infection, we first knocked down the expression of STAT5B and SOCS5 using RNAi in viruliferous SBPHs." (PMID 36928081, 2023). "Our study showed that viral infection activated STAT5B phosphorylation, accelerated BCL2 consumption and triggered subsequent apoptosis response." (PMID 36928081, 2023). "It is intriguing to figure out how viral infection activates STAT5B phosphorylation in SBPH vectors." (PMID 36928081, 2023). "Whether there is a similar mechanism to active STAT5B phosphorylation in response to viral infection requires further investigation." (PMID 36928081, 2023). "Based on these reports, we may speculate that rare long-lived cell clones with BACH2 or STAT5B activating viral insertions and harboring an infectious viral genome could exist and sustain viral infection during years." (PMID 28887441, 2017). "Since STAT5B is paramount in signaling of IL-2 and IL-15—which are key growth factors for T and NK cells respectively—, moderate CD4+, CD8+, and NK cell lymphopenia is frequently displayed, potentially explaining the increased susceptibility to viral infections." (PMID 34277517, 2021). "Associated with transcriptionally regulatory network, ISG15 expression which was targeted by STAT5B and GATA2 factors was induced by virus infection." (PMID 25907774, 2015). "In the present study, our findings revealed for the first time that STAT5a, but not STAT5b, regulated the expression of key factors involved in the immune response after virus infection." (PMID 33317444, 2020). "A propensity to develop viral infections—however—is not so evident in IPEX and STAT5B deficiencies." (PMID 34277517, 2021).
autoimmune disease (7 papers, 2012 to 2023). A disorder resulting from loss of function or tissue destruction of an organ or multiple organs, arising from humoral or cellular immune responses of the individual to their own tissue constituents. "Expansions of CD4+ LGL rarely manifest neutropenia or autoimmune diseases, but frequently co-occurred with solid tumors and often displayed STAT5B but not STAT3 mutations." (PMID 34359799, 2021). "The specific role that STAT5b plays in the pathogenesis of the autoimmuned diseases suggested that the transcription factor might have potential as a novel diagnostic and/or therapeutic target in some disease settings." (PMID 32646440, 2020). "This is in line with some STAT5B LOF human patients that show high levels of IgG and activated T cells along with autoimmune disease." (PMID 36995466, 2023). "All STAT family members (STAT1, STAT2, STAT3, STAT4, STAT5A, STAT5B, and STAT6) are related to autoimmune diseases." (PMID 35204186, 2022). "The STAT5b–MKL-1 interaction identifies a role of Treg-specific gene regulation and regulated mouse Treg cell development and function and suggests a possible mechanism for the protective effects of autoimmune disease Idiopathic Thrombocytopenic Purpura (ITP)." (PMID 32646440, 2020). "Collectively, we demonstrate the pivotal role of the STAT5b–MKL-1 interaction identifies a role of Treg-specific gene regulation and regulated Treg cell development and function and suggests a possible mechanism for the protective effects of autoimmune disease ITP." (PMID 32646440, 2020). "However, the molecular mechanisms mediating STAT5b-dependent Treg genes expression and Treg cell phenotype and function in autoimmune diseases are not well defined." (PMID 32646440, 2020).
T-cell acute lymphoblastic leukemia (7 papers, 2016 to 2022). Acute lymphoblastic leukemia of T-cell origin. "The STAT5B N642H mutation is also frequently detected in pediatric T-cell acute lymphoblastic leukemia and has been associated with an increased risk of recurrence." (PMID 36232600, 2022). "For example, the identification of a STAT5B mutation in a 5-year-old girl erroneously diagnosed with T-cell ALL helped to establish a diagnosis of gamma-delta T-cell lymphoma." (PMID 28007021, 2016).